MCRS1 (microspherule protein 1)
Diseases named in the same sentence as MCRS1 in open-access papers:
MCRS1 is named in the same sentence as 21 diseases in open-access papers, as found by Europe PMC text mining. Sharing a sentence is not in itself a finding about the gene and the disease. The quoted sentences say what the papers report.
lung carcinoma (5 papers, 2014 to 2022). "MCRS1 have been implicated in epithelial-mesenchymal transition, metastasis and growth of lung cancer cells." (PMID 29871630, 2018). "In lung cancer, liver cancer, and glioma cells, decreased MCRS1 expression can inhibit cell growth and increase the occurrence of apoptosis of cancer cells." (PMID 35741311, 2022). "In early studies, we screened novel cancer-related genes and found that microspherule protein 1 (MCRS1) was overexpressed in lung cancer." (PMID 28736730, 2017). "In previous studies, we screened novel lung cancer-related genes using a combination of cytogenetic and molecular genetic methods and found that microspherule protein 1 (MCRS1) was overexpressed in NSCLCs." (PMID 26467212, 2015). "We examined the expression of these miRNAs in a series of lung cancer cell lines and found that the expression of miR-129* correlated inversely with MCRS1 expression." (PMID 25373388, 2014). "This miR-129*/MCRS1/miR-155 axis provides a new angle in understanding the basis for the invasion and metastasis of lung cancer." (PMID 25373388, 2014). "Our previous study demonstrated that miR-155 is a downstream node of MCRS1 in lung cancer cells." (PMID 26467212, 2015). "The levels of MCRS1 expression were first determined in 7 lung cancer cell lines and 16HBE." (PMID 25373388, 2014). "Thus, there is the MCRS1–miR-155–Rb1 pathway in lung cancer." (PMID 28736730, 2017). "Next, we clarified the mechanisms by which MCRS1 silencing inhibited tumor proliferation through comparing the mRNA expression profiles of cultured lung cancer cells with or without MCRS1 silencing." (PMID 26467212, 2015).
glioma (4 papers, 2012 to 2022). A benign or malignant brain and spinal cord tumor that arises from glial cells (astrocytes, oligodendrocytes, ependymal cells). "In 55 patients with glioma, MCRS1 expression positively correlated with Ki-67, indicating a role for MCRS1 in tumor proliferation." (PMID 35741311, 2022). "Similarly, MCRS1 depletion in glioma cells results in reduced tumorigenicity both in vitro and in nude mouse models." (PMID 31267707, 2019).
non-small cell lung carcinoma (3 papers, 2014 to 2022). A group of at least three distinct histological types of lung cancer, including non-small cell squamous cell carcinoma, adenocarcinoma, and large cell carcinoma. "In non-small cell lung cancer, MCRS1 binds to the miR-155 promoter, regulates miR-155, promotes the expression of EMT protein, and increases invasiveness and metastasis of tumors." (PMID 35741311, 2022). "MCRS1 is overexpressed in non-small cell lung cancer (NSCLC) and promotes the growth of cancer cells." (PMID 26467212, 2015). "In this study, we observed that an overexpression of microspherule protein 1 (MCRS1) promotes the invasion and metastasis of non-small cell lung cancer (NSCLC) cells." (PMID 25373388, 2014).
breast carcinoma (2 papers, 2022 to 2026). "Mechanistically, BAP1 has been found to deubiquitylate both gamma‐tubulin in breast cancer and the centrosome protein MCRS1 in renal cell carcinoma, affecting the mitotic spindle and centrosome formation." (PMID 35474453, 2022).
colorectal cancer (2 papers, 2012 to 2015). A primary or metastatic malignant neoplasm that affects the colon or rectum. "Mounting evidence has demonstrated that MCRS1 is overexpressed in human esophageal carcinomas, hepatocellular carcinomas and colorectal carcinomas." (PMID 26467212, 2015).
chronic lung disease (1 paper, 2018). According to the definitions of the American and British Thoracic Societies, including pulmonary functional tests, X-rays, and CT scans for items such as fibrosis, bronchiectasis, bullae, emphysema, nodular or lymphomatous abnormalities. "Based on the hypothesis on the origin of chronic lung diseases like COPD during the early life events, we could detect three novel (HJURP, MCRS1 and TLR8) COPD candidate genes and replicate the findings in 17 other studies using a mouse-human translational datamining approach." (PMID 29871630, 2018).
gastric cancer (1 paper, 2022). A primary or metastatic malignant neoplasm involving the stomach. "The high expression of MCRS1 increased the risk of death by 2.44 times compared with the low expression group at the same time after suffering from gastric cancer." (PMID 35741311, 2022). "High MCRS1 expression in gastric cancer positively correlated with Ki-67, Caspase3, CD31, Fibronectin, pAKT, and pAMPK." (PMID 35741311, 2022). "In this article, we will use immunostaining analysis of excised tissue from gastric cancer patients to better clarify the role of MCRS1 in tumors." (PMID 35741311, 2022). "Western blotting confirmed that the expression of MCRS1 in gastric cancer cell lines was higher than that in normal cells." (PMID 35741311, 2022). "Overexpression of MCRS1 in gastric cancer has been proposed to increase tumor proliferation, metastasis and invasion." (PMID 35741311, 2022). "This is the first study to use human tumor specimens to assess the expression of MCRS1 and other markers, and our findings confirm that MCRS1 is associated with Ki-67, Caspase3, CD31, fibronectin, pAKT, and pAMPK in gastric cancer." (PMID 35741311, 2022). "In conclusion, the high expression of MCRS1 in gastric cancer was positively correlated with Ki-67, Caspase3, CD31, fibronectin, pAKT and pAMPK." (PMID 35741311, 2022). "Although there have been previous reports that MCRS1 is involved in gastric cancer proliferation, metastasis, and invasion, these reports are limited to cell experiments." (PMID 35741311, 2022). "In patients with gastric cancer, elevated MCSR1 is associated with increased mortality risk compared to lower MCRS1 expression." (PMID 35741311, 2022). "In addition, in previous studies, the related studies of MCRS1 in gastric cancer were limited to cell lines." (PMID 35741311, 2022). "High expression of MCRS1 in gastric cancer increases the expression of Ki-67, Caspase3, CD31, fibronectin, pAKT, and pAMPK; therefore, MCRS1 positively correlates with these proteins." (PMID 35741311, 2022). "Although we did not further explore the mechanism of Ki-67 in gastric cancer in this study, our experiments confirmed that the high expression of MCRS1 affects the prognosis of patients, and the influence of Ki-67 is also involved." (PMID 35741311, 2022).
pancreatic cancer (1 paper, 2025). "Microspherule protein 1 (MCRS1) enhances MHC‐I expression and T cell‐mediated immunity in pancreatic cancer by interacting with YY1, a transcription factor, to increase chromatin accessibility at MHC‐I gene loci." (PMID 40673641, 2025).
Wilms tumor (1 paper, 2021). An embryonal neoplasm characterized by the presence of epithelial, mesenchymal, and blastema components. "Five of seven proven candidates, PEG10, YEATS2, FOXK1, CBLL1 and MCRS1 showed a clear positive correlation of mRNA levels with MYCN in Wilms tumors undergoing the SIOP protocol." (PMID 34689785, 2021).
cancer (10 papers, 2012 to 2026). A tumor composed of atypical neoplastic, often pleomorphic cells that invade other tissues. "Single-cell analysis revealed that Mcrs1 is predominantly expressed in proliferating cancer cells, where it drives a transcriptional program of enhanced cell cycle, senescence, and metabolic reprogramming." (PMID 41556158, 2026). "In each of these cancers, increased levels of MCRS1 correlate with cancer aggressiveness and poor survival." (PMID 31267707, 2019). "It is interesting to note that reduced MOF and H4K16ac levels but increased levels of MCRS1 and KANSL2 are associated with cancer progression and aggressiveness." (PMID 31267707, 2019). "Based on the transformative properties of MCRS1 and its biological roles in various types of human cancers, MCRS1 can be considered a candidate oncogene." (PMID 26467212, 2015). "The DNA copy number and the level of mRNA expression of MCRS1 were markedly elevated in each cancer cell line compared with those of the 16HBE cell line." (PMID 26467212, 2015). "MCRS1 overexpression has been documented in a variety of human cancers, and this overexpression was found to induce the proliferation of cancer cells." (PMID 25373388, 2014). "The metastases in the lung and brain were confirmed by histological examination, and a statistical analysis revealed that MCRS1 silencing dramatically attenuated the ability of the cancer cells to form metastases in the lung and brain." (PMID 25373388, 2014). "Interestingly, in the continuing study, we established that MCRS1 promoted cancer cell growth via miR-155 targeting Rb1." (PMID 28736730, 2017). "Moreover, MCRS1 silencing was reported to suppress the proliferation, migration and invasion of the tumor cells of other types of cancers." (PMID 26467212, 2015).
tumor (9 papers, 2012 to 2026). "Collectively, MCRS1 expressions were associated with the status of tumor metastasis in clinical samples." (PMID 25373388, 2014). "MCRS1 is a validated driver of tumor progression and a high-performance biomarker, representing a potential target for therapeutic development, particularly in BC patients with metabolic comorbidities." (PMID 41556158, 2026). "Fudan University’s team led by Xiao Fei has revealed that MCRS1 can enhance the sensitivity of tumor cells to T-cell killing by upregulating MHC-I molecule expression in solid tumors, while improving the therapeutic effect of PD-1 blockade therapy." (PMID 40027134, 2025). "Most pieces of evidence show that increased fibronectin expression promotes tumor development, but our results show that increased MCRS1 expression is negatively correlated with fibronectin." (PMID 35741311, 2022). "In the future, after clarifying the relevant mechanism, we will try to use MCRS1 as a target to inhibit and develop related drugs for the treatment of tumor growth." (PMID 35741311, 2022). "By selecting IHC staining at the same position of the tumor, we observed the level of MCRS1 expression, which affects the expression of Ki-67, Caspase3, fibronectin, pAKT, and pAMPK." (PMID 35741311, 2022). "A comprehensive understanding of the pathways related to MCRS1 will aid in evaluating the potential of MCRS1 or MCRS1-targeting agents as candidate drugs for inhibiting tumor growth and improving patient survival." (PMID 35741311, 2022). "We immunostained tumor tissues to observe the interactions between MCRS1 and other common proteins involved in proliferation, apoptosis, angiogenesis, epithelial–mesenchymal transition (EMT), and tyrosine kinases." (PMID 35741311, 2022). "The results of the cell proliferation assays showed that MCRS1 silencing significantly decreased the rate of NSCLC tumor cell proliferation in vitro." (PMID 26467212, 2015). "To investigate the effect of MCRS1 on tumor formation, we stably reduced the level of MCRS1 expression using RNA interference mediated by a retroviral system (pSIREN-RetroQ) in EPLC-32 M1, A549 and 801D cells, representing SCC, AC and LCC cells, respectively." (PMID 26467212, 2015). "In this study, downregulating MCRS1 expression significantly inhibited the growth of tumor cells in vitro and in an animal model." (PMID 26467212, 2015). "In our study, E-cadherin was found to be up-regulated at both the mRNA and protein levels after MCRS1 knockdown, suggesting that MCRS1 overexpression can lead to AJ disruption, cellular invasion, and tumor metastasis." (PMID 25373388, 2014). "The miR-129*/MCRS1/miR-155 axis provides a new avenue to understand the mechanism of the tumor invasion and metastasis." (PMID 25373388, 2014). "High expression of MCRS1 increases tumor growth, invasiveness, and metastasis." (PMID 35741311, 2022). "Collectively, the in vitro and in vivo analyses supported the suppressive effect of MCRS1 silencing on tumor cell growth, indicating that MCRS1 expression may play a role in the growth of NSCLC cells." (PMID 26467212, 2015). "Taken together, these results indicated that MCRS1 could affect tumor cell growth through indirectly modulating the expression of pro-proliferative, anti-proliferative and cell cycle-related genes." (PMID 26467212, 2015). "MCRS1 is a candidate oncogene, and Rb1 is one of the most important tumor suppression genes." (PMID 26467212, 2015). "Based on our previous study showing that miR-155 is a downstream mediator of the function of MCRS1 in cellular proliferation and the EMT process, we examined whether MCRS1 regulated tumor cell growth through miR-155 targeting of the Rb1 gene." (PMID 26467212, 2015). "We found that MCRS1 overexpression suppressed the expression of DSG2 mRNA, indicating that MCRS1 overexpression could impair cell adhesion and increase tumor invasion and metastasis." (PMID 25373388, 2014).
tumor (continued). "The levels of MCRS1 expression were likewise correlated with tumor metastasis among NSCLC patients." (PMID 25373388, 2014). "Moreover, miR-155 was up-regulated in NSCLC tissues and cultured cells, and its overexpression was correlated with the MCRS1 expression and the status of tumor metastasis." (PMID 25373388, 2014). "Summarily, these data demonstrated that miR-129* could be a tumor suppressor that affects cellular behavior by modulating MCRS1 expression." (PMID 25373388, 2014). "Thus, we sought to investigate whether MCRS1 promoted tumor growth through miR-155-targeted genes." (PMID 26467212, 2015). "Here, we confirmed that Rb1, an important tumor suppression gene (TSG), is a direct target of miR-155 which is directly up-regulated by MCRS1." (PMID 26467212, 2015). "In our study, MCRS1 overexpression increased epithelial permeability and reduced both ZO-1 and Occludin expression, indicating that MCRS1 overexpression may abolish the functions of TJs and promote cellular invasion and tumor metastasis through the suppression of TJ molecules." (PMID 25373388, 2014). "Altogether, these results indicated that MCRS1 overexpression can influence multiple molecules and pathways and promote the EMT program, cellular invasion, and tumor metastasis." (PMID 25373388, 2014). "MCRS1 overexpression promoted the EMT program and tumor invasion/metastasis in NSCLC cells through the up-regulation of miR-155 and the down-regulation of cell junction molecules." (PMID 25373388, 2014). "In summary, MCRS1 overexpression contributes to the EMT program in NSCLC cells, and this EMT program may be involved in tumor metastasis." (PMID 25373388, 2014). "Additionally, using a Kyoto Encyclopedia of Genes and Genomes (KEGG) analysis we were particularly interested in how cell junctions and Notch signaling were affected by MCRS1 due to their potential roles in EMT and tumor metastasis." (PMID 25373388, 2014). "To gain further insight into whether MCRS1 regulates EMT and tumor metastasis through miRNAs, we primarily determined the miRNA profiles in the EPLC-32 M1 with and without MCRS1 silencing." (PMID 25373388, 2014).
MCRS1 also shares sentences with these, for which no sentence is quoted: cervical cancer (2 papers); esophageal carcinomas (1); glioblastoma (1); hepatocellular carcinoma (1); liver cancer (1); liver cirrhosis (1); lymph node metastasis (1); metabolic syndrome (1); oral cavity squamous cell carcinoma (1); renal cell carcinoma (1).